LONP1 (lon peptidase 1, mitochondrial)
Diseases named in the same sentence as LONP1 in open-access papers (continued):
Sharing a sentence is not in itself a finding about the gene and the disease.
tumor (continued). "Thus, our finding that the deacetylation of LONP1 by Sirt3 constrains carcinogenesis need to be confirmed in other tumor cell lines." (PMID 36739437, 2023). "LonP1 further regulates carcinogenesis by modulating the bioenergetics of tumor cells." (PMID 36362158, 2022). "Finally, inhibiting proteolysis by targeting LONP1 increases mitochondrial content in VHL-deficient cells and sensitizes therapy-resistant tumours to sorafenib treatment." (PMID 35760869, 2022). "Studies revealed that LonP1 also plays a critical function in tumor cells by controlling bioenergetics and its upregulation induces profound changes in mitochondrial protein complexes, leading to the inactivation of mitochondrial respiration and favoring the glycolytic switch." (PMID 33547867, 2021). "PANC1 cells with LONP1 interference were less sensitive to erastin than control cells, but GPX4 expression and the GSH content were increased; thus, LONP1 was concluded to induce a tumour suppressor effect by downregulating GPX4 expression and reducing the GSH content." (PMID 34503532, 2021). "This metabolic re-modelling might be the basis of the lack of proliferative capacity of cells with a reduced expression of Lonp1 when a tumor develops." (PMID 32521756, 2020). "These functions enable LonP1 to mediate vital physiological processes such as cellular respiration, cellular metabolism, and oxidative stress, but also to contribute to certain diseases, including neoplasms, developmental defects, neurodegenerative diseases, and cardiac disorders." (PMID 36362158, 2022). "In addition, elevated LONP1 expression increases the level of ROS to promote the production of inflammatory cytokines, including TGF-β and IL-6, thus boosting the activation of M2 macrophages and establishing an immunosuppressive tumor microenvironment." (PMID 35180892, 2022).
neurological diseases (4 papers, 2019 to 2024). "Future studies are needed to elucidate the role of LONP1 in other neurological diseases and the underlying regulatory mechanisms for its expression and activity." (PMID 31387295, 2019). "Indeed, impairment of LONP1 results in the accumulation of toxic proteins and an extensive apoptotic death via caspase-3 activation, which is associated with a number of neurological diseases." (PMID 33668863, 2021). "Therefore, we provide an underlying mechanism of CDDO-Me for mitochondrial fission independent of LONP1 activity, and propose the availability of CDDO-Me for various neurological diseases relating to aberrant mitochondrial dynamics." (PMID 31387295, 2019).
mitochondrial disease (3 papers, 2023 to 2025). "While LONP1 has a clear association with mitoribosome biogenesis, patients carrying mutations in LONP1 display atypical pathologies uncommon to mitochondrial disease, highlighting the broader potential physiological significance of the protein." (PMID 40857737, 2025).
cardiovascular diseases (2 papers, 2023 to 2024). "Finally, we discuss the role of Lonp1 in the aging process, and the functional outcomes of the age-related Lonp1 expression decline in the onset of cardiovascular diseases and skeletal muscle functional decline." (PMID 36978846, 2023).
infection (2 papers, 2023 to 2024). The state of being infected such as from the introduction of a foreign agent such as serum, vaccine, antigenic substance or organism. "We next asked if silencing LONP1 could reduce inflammation during infection and found that IL-6 production was dampened upon S. Typhimurium infection by silencing LONP1 or pharmacologically inhibiting LONP1, or upon inhibition of complex I using Rotenone." (PMID 38263327, 2024). "In addition to irg-1, the infection response gene-2 (irg-2), another ZIP-2 target, was upregulated upon lonp-1 deletion." (PMID 38139038, 2023). "However, the increased activity of ATFS-1 and ZIP-2 in the lonp-1 background was not sufficient to promote host resistance to infection by the P. aeruginosa strain PA14, and lonp-1 adults were significantly susceptible to the pathogen compared to wt animals." (PMID 38139038, 2023).
kidney diseases (2 papers, 2024 to 2025). "Lon protease 1 (LONP1) is a mitochondrial protease that plays a key role in maintaining mitochondrial homeostasis; however, its role in endothelial dysfunction-related renal disease is unknown." (PMID 41275592, 2025). "Recently, there has been a cumulative indication that LONP1 is responsible for kidney diseases." (PMID 39261902, 2024).
adenocarcinoma (1 paper, 2018). A common cancer characterized by the presence of malignant glandular cells. "Forced LonP1 expression led to increased β-ctn levels, reduced E-cadherin, and increased N-cadherin in primary adenocarcinoma cells SW480." (PMID 30038898, 2018).
blood cancers (1 paper, 2022). "The overexpression of LonP1 has been observed in numerous solid tumors and blood cancers and is postulated to be a risk factor for promoting oncogenesis." (PMID 35151690, 2022). "In addition, the upregulation of LonP1 has been observed in various solid tumors and blood cancers and is postulated to be a risk factor for promoting oncogenesis." (PMID 35151690, 2022).
LONP1 also shares sentences with these, for which no sentence is quoted: glioblastoma (3 papers); Insulin resistance (3); leukemia (3); cardiac disease (2); chronic kidney disease (2); genetic disease (2); lactic acidosis (2); lung carcinoma (2); metabolic disorders (2); pancreatic ductal adenocarcinoma (2); acute kidney injury (1); acute myeloid leukemia (1); amyotrophic lateral sclerosis (1); atrial fibrillation (1); B-cell lymphoma (1); bacterial infection (1); bone metabolic disorders (1); Cerebral ischemia (1); cervical cancer (1); clear cell renal cell carcinoma (1); Cognitive impairment (1); Death (1); developmental delay (1); diabetic kidney disease (1); energy metabolism disorders (1); Epileptic encephalopathy (1); even-plus syndrome (1); gastric diseases (1); glomerulopathy (1); Hypertension (1).
A further 20 diseases each share a sentence with LONP1 in 1 paper.